ROS1 (ROS proto-oncogene 1, receptor tyrosine kinase)
Diseases named in the same sentence as ROS1 in open-access papers (continued):
Sharing a sentence is not in itself a finding about the gene and the disease.
non-small cell lung carcinoma (continued). "Based on a literature search, chromosomal rearrangements involving the ROS1 gene were first described in non-small cell lung carcinoma (NSCLC), and CD74-ROS1 fusion transcripts were also detected in NSCLC." (PMID 34051833, 2021). "It occurs in approximately 1% of patients with non-small cell lung carcinoma (NSCLC), and treatment with ROS1 inhibitors prolongs progression-free survival." (PMID 30443294, 2018). "The ALK/MET/ROS1 inhibitor crizotinib is approved for the treatment of non-small cell lung carcinoma (NSCLC) with ALK translocations and is also being tested in neuroblastoma (clinical trial: NCT00939770)." (PMID 29515255, 2018). "Crizotinib, a FDA approved drug for treatment of Non-Small Cell Lung Carcinoma (NSCLC) patients with rearranged ROS1 was used to treat these resistant cells and showed a moderate effect compared to the pyrazole ROS1 inhibitor." (PMID 25978031, 2015). "Also crizotinib has shown potent antitumor activity in a second subgroup of patients with non-small-cell lung cancer (NSCLC)—those with advanced ROS1 protooncogene receptor tyrosine kinase- (ROS1-) rearranged tumors, which are found in about 1% of NSCLC patient adenocarcinomas." (PMID 25861506, 2015). "Over the past two decades, marked progress has been made in treating non-small cell lung cancer (NSCLC) patients with EGFR-, ALK-, ROS1- and KRASG12C-targeted inhibitors." (PMID 40893689, 2025). "Entrectinib, a CNS-penetrant tyrosine kinase inhibitor with potent activity against TRK, ROS1, and ALK fusion proteins, has demonstrated efficacy in NTRK-rearranged solid tumors such as non-small cell lung cancer and secretory carcinomas." (PMID 41397922, 2025). "For instance, reduced m6A levels enhances the therapeutic efficacy of crizotinib, an ALK/ROS1/c-MET kinase inhibitor, in the treatment of non-small cell lung cancer (NSCLC) with high c-MET expression." (PMID 40533443, 2025). "A similar approach is taken toward MET, HER2, RET, ROS1, and FGFR alterations as emerging targets in non-small-cell lung cancer." (PMID 39941723, 2025). "Crizotinib is an oral small-molecule tyrosine kinase inhibitor of the ALK, MET, and ROS1 kinases, approved in ALK-positive non-small cell lung cancer." (PMID 38928438, 2024). "The ALK, ROS1 and RET kinase fusion are crucial biomarkers that can predict the function of tyrosine kinase inhibitors (TKIs) in the non-small-cell-lung cancer (NSCLC)." (PMID 37091783, 2023). "As an oral small-molecule tyrosine kinase inhibitor, Crizotinib, targeting the ALK, ROS1 and MET tyrosine kinases, is well approved to induce clinically significant responses in non-small cell lung cancer." (PMID 37950305, 2023). "In addition to common EGFR activation mutations, targets such as ALK rearrangement, ROS1 rearrangement, RET rearrangement, BRAF V600E, MET exon 14 skip mutation, KRAS G12C, etc. have been gradually approved for targeted drug application in advanced non-small cell lung cancer." (PMID 38023198, 2023). "The development of targeted therapies has led to personalized medicine for advanced non-small cell lung cancer (NSCLC), particularly in lung adenocarcinoma (ADC) with actionable genetic alterations, such as EGFR, ALK, KRAS, and ROS1." (PMID 37345086, 2023). "For example, although Swedish non-small cell lung cancer guidelines recommend NGS-based genomic testing for EGFR, KRAS, BRAF, ALK, NTRK, and ROS1, guidelines in Norway only include EGFR, ALK, and ROS1." (PMID 35055387, 2022). "ROS1 and ALK rearrangements account, respectively, for 2–3% and 3–7% of non-small cell lung cancer cases." (PMID 36142468, 2022). "The detection of ROS1 and ALK rearrangements is performed for advanced-stage non-small cell lung cancer." (PMID 36142468, 2022).
non-small cell lung carcinoma (continued). "Accordingly, crizotinib, an FDA-approved drug used for the treatment of patients with ALK-positive and ROS1-positive non-small cell lung carcinoma (NSCLC), triggered the nuclear translocation of FOXO3 suggesting an important role of RTKs such as ALK, MET or ROS1 in the regulation of FOXO3." (PMID 36080182, 2022). "Targeted therapy for non-small-cell lung cancer (NSCLC) involves drugs that inhibit angiogenesis, and inhibitors of kinases EGFR, ROS1, MET, and RET." (PMID 35740471, 2022). "Particularly in advanced Non-Small Cell Lung Cancer (NSCLC), treatment options have evolved with epidermal growth factor receptor (EGFR), anaplastic lymphoma kinase (ALK)- and ROS proto-oncogene 1 (ROS1) directed treatment." (PMID 35008297, 2021). "Treatment planning for non-small cell lung cancer requires testing for EGFR, ALK, ROS1, BRAF, MET, RET and KRAS gene alterations." (PMID 34681592, 2021). "Crizotinib was approved for metastatic anaplastic lymphoma kinase (ALK)-positive non-small cell lung cancer (NSCLC) in 2011 and metastatic ROS proto-oncogene 1 receptor tyrosine kinase (ROS1)-rearranged NSCLC in 2016." (PMID 34771620, 2021). "In non-small cell lung cancer (NSCLC) determination of biomarkers such as ALK, EGFR, ROS1 or PD-L1 is mandatory for an adequate treatment decision." (PMID 34112097, 2021). "Abnormal fusion genes such as ALK, ROS1, and NTRK are commonly observed in subsets of patients with non-small cell lung cancer (NSCLC)." (PMID 33627640, 2021). "The kinase targets in non-small cell lung cancer (NSCLC) include epidermal growth factor receptor (EGFR), anaplastic lymphoma kinase (ALK) and ROS proto-oncogene 1 (ROS1)." (PMID 32595510, 2020). "Non-small cell lung carcinoma (NSCLC) harboring rearrangements of the anaplastic lymphoma kinase (ALK) gene and the ROS1 oncogene constitute a unique molecular subgroup of this patient population." (PMID 29774128, 2018). "ROS1 fusions are detected in ~2% of non-small cell lung carcinoma (NSCLC) patients." (PMID 29654269, 2018). "Oncogenic ROS1 and NTRK fusions were reported in solid tumors, including non-small cell lung cancer (NSCLC)." (PMID 29805770, 2018). "Non-small cell Lung cancer is now a heterogenous disease with EGFR, BRAF, Her2/Neu aberrations or ALK, ROS1, RET or FGFR fusions." (PMID 26510912, 2015). "In this regard, we note that ROS1 tyrosine kinase is sensitive to the existing ALK small-molecule inhibitor, crizotinib, and indeed a single patient's non-small cell lung cancer harboring a ROS1 fusion was found to be responsive." (PMID 23637631, 2013). "ROS1 rearrangements define a distinct, targetable subset of non-small cell lung cancer (NSCLC), representing ~2% of non-squamous cases and frequently presenting with metastatic disease and CNS involvement." (PMID 41704605, 2026). "Likewise, the evaluation of genes such as ALK, ROS1, RET, and HER2 is crucial in assessing non-small-cell lung cancer (NSCLC), as established in the National Comprehensive Cancer Network (NCCN) guidelines." (PMID 39338229, 2024). "Repotrectinib has been approved for use in adult patients with locally advanced or metastatic ROS1-positive non-small-cell lung cancer, although not all G2032R patients respond to this treatment." (PMID 38791529, 2024). "For non-small cell lung cancer (NSCLC), this has led to the development of tyrosine kinase inhibitors (TKIs) specifically targeting the resulting fusion proteins, including ALK, ROS1, RET, and NTRK." (PMID 37016288, 2023). "Despite the success of targeted therapy in c-ros oncogene 1 (ROS1)-rearranged cancers, especially non-small cell lung cancer (NSCLC), the clinical significance of ROS1 de novo mutation has not yet been understood." (PMID 34221982, 2021). "ROS1 fusion was detected in 2.59% of Chinese non-small cell lung cancer (NSCLC) patients but has not been found in TNBC patients before." (PMID 34396843, 2021).
non-small cell lung carcinoma (continued). "Recent examples include NTRK fusions (e.g., 0.5–4% of colorectal cancer), ROS1 (1–2% of Non-small-cell lung carcinoma), and ALK (~4% of Non-small-cell lung carcinoma), all of which have therapeutics currently in the clinic." (PMID 34504101, 2021). "While no direct comparative data exist for crizotinib in ROS1+ non-small cell lung cancer (NSCLC), studies have suggested clinical benefit with this targeted agent." (PMID 34715804, 2021). "Crizotinib is already licensed in the treatment of non-small cell lung cancer and, if found to be effective in the treatment of ILC, may result in further trials investigating the inhibition of ROS1 as a novel therapeutic strategy for ILC." (PMID 33520704, 2020). "Other frequently recurring fused kinases are ALK (found in 18 cell lines) and ROS1 (in 6 cell lines), both well known as cancer drivers in lung adenocarcinoma (EML4-ALK fusion) and non-small cell lung cancer (ROS1 rearrangements), for which different inhibitor drugs have been developed." (PMID 33257674, 2020). "In order to assess the utility of this system for analysis of targeted therapies, we subjected two established non-small cell lung cancer cell lines H522 and H3122 to crizotinib treatment, a tyrosine kinase inhibitor (TKI) with activity against ALK, ROS1 and CMET." (PMID 27548442, 2016). "ROS proto-oncogene 1 (ROS1) fusions are oncogenic drivers that have been identified in around 2% of patients with non-small-cell lung cancer and are more prevalent in non-squamous tumor types, younger individuals, female patients, and those without a history of smoking." (PMID 40075596, 2025). "Crizotinib is an anti-cancer medication approved by the FDA in January 2021 for non-small cell lung carcinoma (NSCLC) treatment through the inhibition of both anaplastic lymphoma kinase (ALK) and c-ros oncogene 1 (ROS1)." (PMID 39860235, 2025). "Likewise, it has been found that the newer targeted therapy, including inhibitors of EGFR, ALK, PI3K/AKT/mTOR, RAS-MAPK, RET, MET, BRAF, and NTRK/ROS1, as well as PD1 and CTLA4 molecules, for non-small cell lung cancer (NSCLC) have far better treatment responses than the standard therapies." (PMID 39157206, 2024). "The main druggable genetic alterations in non-small cell lung cancer involved EGFR (epidermal growth factor receptor), KRAS (Kirsten rat sarcoma viral oncogene homolog), ALK (anaplastic lymphoma kinase), BRAF (V-raf murine sarcoma oncogene homolog B1), and ROS1 (c-ros oncogene 1) genes." (PMID 39199653, 2024). "In non-small cell lung carcinoma (NSCLC), targeted therapies are mainly directed toward specific altered genes that have been thoroughly analyzed, including EGFR, ALK, ROS1, and RET." (PMID 37999148, 2023). "In non-small cell lung carcinoma (NSCLC), the gene fusions of ALK, NTRK, RET, and ROS1 are detected with the approximate frequencies of 4–6, 1, 1–2, and 1–2%, respectively." (PMID 32328458, 2020). "The detection of ROS1 rearrangements in metastatic non-squamous non-small cell lung carcinoma (NS-NSCLC) permits administration of efficient targeted therapy." (PMID 37240980, 2023). "Patients with advanced non-small cell lung cancer and programmed cell death-ligand 1 expression ≥50% received cemiplimab monotherapy (n=283), and patients with no EGFR, ALK, or ROS1 genomic aberrations received cemiplimab plus chemotherapy (n=312)." (PMID 41194933, 2025). "Molecular analysis of NTRK fusion-positive non-small-cell lung cancers showed no concurrent alterations in KRAS, EGFR, ALK, and ROS1 or other known oncogenic drivers." (PMID 34531526, 2022).
lung adenocarcinoma (159 papers, 2011 to 2026). A carcinoma that arises from the lung and is characterized by the presence of malignant glandular epithelial cells. "Herein, we report a case of advanced lung adenocarcinoma associated with the MPRIP-ROS1 fusion gene, a rare ROS1 rearrangement, detected using a comprehensive genomic profiling test in a patient with remarkable tumor response to crizotinib." (PMID 40678598, 2025). "These subgroups were chosen for comparative analysis because ALK and ROS1 fusions are well‐validated fusion genes in lung adenocarcinoma, whereas EGFR mutations are a commonly validated driver gene primarily receiving targeted therapy." (PMID 40751559, 2025). "Our findings indicate that among patients with advanced lung adenocarcinoma harboring driver genes, those with ROS1 fusions exhibited the highest peri‐diagnostic and overall cumulative incidence of TEs." (PMID 40751559, 2025). "Herein, we report a case of a lung adenocarcinoma patient harboring a rare ROS1 fusion mutation with brain metastasis, who achieved good control of both lung and intracranial lesions after treatment with Entrectinib." (PMID 40308505, 2025). "ROS1 fusions exhibited the highest peri‐diagnostic and overall cumulative incidence of TEs among patients with advanced lung adenocarcinoma harboring driver genes." (PMID 40751559, 2025). "Molecular profiling for driver mutations such as EGFR, ALK, and ROS1 is essential in advanced lung adenocarcinomas." (PMID 40949067, 2025). "A diagnosis of ROS1-rearranged adenocarcinoma of the lung was made from the pathological and gene mutation analyses of the cell block from his pericardial fluid." (PMID 39559635, 2024). "EGFR, ALK, BRAF, KRAS, ROS1 are the five common genes in lung adenocarcinoma, and EGFR gene mutation is the most common." (PMID 37340599, 2023). "Common driver mutations (EGFR, ALK, BRAF, ERBB2, KRAS, MET, RET, and ROS1) analysis were performed in lung adenocarcinoma tissue samples from two PEAC patients (P08 and P10) using next-generation sequencing." (PMID 35172862, 2022). "ROS1 rearrangements have been identified as driver mutations, accounting for 1-2% of lung adenocarcinoma, but are extremely rare in case of lung squamous cell carcinoma." (PMID 34235088, 2021). "Other, less frequent mutations such as RET and ROS1, which comprise 1–2% of all lung adenocarcinomas, have also been assessed for associations with imaging features." (PMID 31901171, 2020). "Mutations in 59 cancer-associated genes and fusions of ALK and ROS1 were analyzed to understand the molecular features of young patients with lung adenocarcinoma." (PMID 31387567, 2019). "All these three drugs have shown a significant anti-tumor activity in ROS1-mutated lung adenocarcinomas." (PMID 30060526, 2018). "At least 55 partner genes have been identified that can fuse with ROS1.Herein, we report a case of a lung adenocarcinoma patient harboring a rare ROS1 fusion mutation with brain metastasis, who achieved good control of both lung and intracranial lesions after treatment with Entrectinib." (PMID 40308505, 2025). "In this retrospective study of 546 lung adenocarcinoma patients with four different driver genes, ROS1 rearrangements were associated with the increased risk of thromboembolic events (TEs), particularly during the peri‐diagnostic period (6 months before and after diagnosis)." (PMID 40751559, 2025). "A ROS1-rearranged mutation is a rare gene mutation found in about 2% of lung adenocarcinomas." (PMID 39559635, 2024). "Therefore, the purpose of our study was to investigate the differences in CT characteristics and disease spread patterns between patients with lung adenocarcinoma who have ROS1 rearrangement and those with EGFR mutations or ALK rearrangement." (PMID 33005033, 2020).
lung adenocarcinoma (continued). "The results of our study highlight that hepatoid cytology and cribriform structure may be the key morphologic features associated with advanced lung adenocarcinomas with ROS1 rearrangement." (PMID 27708233, 2016). "Interestingly, most of these strongly staining RTKs were mutually exclusive, evoking the oncogenic driver mutations (EGFR, KRAS, ALK, and ROS1) observed in lung adenocarcinoma." (PMID 25989941, 2015). "Additionally, lung adenocarcinomas with calcification may be associated with ROS1 fusions as well as EGFR mutations and ALK fusions." (PMID 39391406, 2024). "Moreover, the co-existence of EGFR gene mutations, ALK gene fusions, and ROS1 gene rearrangements has been reported in a few lung adenocarcinoma cases, but the co-alteration of ROS1, EGFR, and EML4-ALK in MPA remains unclear." (PMID 32677962, 2020). "Since ROS1-positive tumours are very sensitive to treatment with tyrosine kinase inhibitors such as crizotinib, detecting this rare genetic alteration may be an important step in the diagnostic work-up of a patient with lung adenocarcinoma." (PMID 27535289, 2016). "Here, we report an unusual case of a lung adenocarcinoma displaying a strong nuclear staining pattern on ROS1 IHC." (PMID 42254076, 2026). "Current targeted therapies for LUSC harboring ALK, ROS1, or EGFR mutations are typically guided by protocols established for lung adenocarcinoma." (PMID 41868215, 2026). "ROS1 (ROS Proto-Oncogene 1, Receptor Tyrosine Kinase) drives lung adenocarcinoma when ROS1 signaling is constitutively activated, promoting proliferation and survival." (PMID 41154602, 2025). "Common mutation types in lung adenocarcinoma include epidermal growth factor receptor (EGFR), anaplastic lymphoma kinase (ALK) rearranged, and C-ros oncogene 1-receptor tyrosine kinase (ROS1) fusion." (PMID 40134592, 2025). "Crizotinib, on the other hand, inhibits tumor progression by inhibiting ROS1 or ALK and has been approved for the treatment of advanced lung adenocarcinoma patients with c-ROS1 (ROS1) and anaplastic lymphoma kinase (ALK) gene rearrangements." (PMID 40696350, 2025). "This retrospective study aimed to investigate this association in advanced lung adenocarcinoma patients with ALK, ROS1, RET rearrangements, and EGFR mutations." (PMID 40751559, 2025). "In a series of lung adenocarcinoma patients metastatic to the spine with mutational data for selected markers (ALK, MET, ROS1, EGFR, and KRAS), the presence of clinically targetable mutations was found to be associated with increased survival." (PMID 40647516, 2025). "Clinical trials such as BFAST, STARTRK-1, and STARTRK-2 have shown that entrectinib is highly effective in patients with ROS1-fusion lung adenocarcinoma." (PMID 40308505, 2025). "ROS1 encodes a receptor tyrosine kinase of the insulin receptor family and is located on chromosome 6q22; fusions involving ROS1 have been reported in lung adenocarcinoma, glioblastoma, IMT, and cholangiocarcinoma." (PMID 38390852, 2024). "Although keystone findings in the initiation and evolution of lung adenocarcinoma have been recently published, little attention is paid to ROS1-driven tumors." (PMID 39737401, 2024). "Adenocarcinomas with psammoma bodies are often associated with tyrosine kinase inhibitor-targetable driver mutations in EGFR (69.8%), ALK (13.2%), and ROS1 (1.9%), although the presence of psammoma bodies in ROS1-fused lung adenocarcinomas remains debated." (PMID 39391406, 2024). "To complement the initial findings, we expanded the GSEA-based analysis to identify significantly upregulated or downregulated pathways in ROS1+ lung adenocarcinomas and cell lines in comparison to ALK/RET+ tumor samples." (PMID 39737401, 2024).